MET (MET proto-oncogene, receptor tyrosine kinase)
Diseases named in the same sentence as MET in open-access papers (continued):
Sharing a sentence is not in itself a finding about the gene and the disease.
non-small cell lung carcinoma (continued). "MET inhibitors have demonstrated success, particularly in the treatment of non-small cell lung cancer, and therefore, despite their rare use in CCA, they may be a promising therapy for its subset of cancers." (PMID 38339363, 2024). "EMA recently approved the use of tepotinib in MET exon-14-skipping non-small-cell lung cancer." (PMID 37046637, 2023). "Deletion of KMT5C in non-small cell lung cancer promotes resistance to EGFR inhibitors through the LINC01510/MET axis, which could lead to improved mechanistic insights into NSCLC therapy." (PMID 36941564, 2023). "This study aimed to evaluated the safety, tolerability, efficacy and pharmacokinetics (PK) of BPI-9016M, a novel tyrosine kinase inhibitor (TKI) targeting c-MET, in c-MET overexpression or MET exon 14 skipping mutation patients with locally advanced or metastatic non-small-cell lung cancer (NSCLC)." (PMID 37041472, 2023). "In a small number of HNCs, the MET (MET Proto-Oncogene, Receptor Tyrosine Kinase) gene transcript with missing exon 14, a form recognized as oncogenic in non-small cell lung cancer, and mRNAs of TP63 and KLK12 (Kallikrein Related Peptidase 12) genes as specific splicing variants have been reported." (PMID 38179168, 2023). "In non-small cell lung cancers (NSCLCs), up to 5% of the tumors harbor MET amplification." (PMID 37944528, 2023). "In cholangiocarcinoma, mesenchymal–epithelial transition factor (MET) amplification may present an additional opportunity for a targeted therapeutic approach, especially considering emerging data in non-small cell lung cancer." (PMID 35129063, 2022). "Additionally, the use of the combination of GW-2974 with a MET inhibitor, yielded maximum growth inhibition in the treatment of non-small cell lung carcinoma (NSCLC) than the use of any individual inhibitor." (PMID 36476719, 2022). "Amivantamab, available under the brand name Rybrevant, is a human IgG1-based bispecific monoclonal antibody which simultaneously targets both EGFR and the mesenchymal–epithelial transition (MET) receptor expressed on the surface of epithelial cells in non-small-cell lung cancer (NSCLC)." (PMID 36498915, 2022). "Beyond the scope of mRCC, 68Ga-EMP-100 PET could also be used in other tumor entities with known c-MET expression such as non-small cell lung cancer or differentiated thyroid cancer." (PMID 34708249, 2022). "Increased activity of MET has been previously reported to mediate resistance to EGFR inhibitors (e.g. osimertinib) in non-small cell lung cancer via EGFR-independent phosphorylation of HER3 and PI3K/Akt activation, providing a bypass pathway in the presence of an EGFR inhibitor." (PMID 33898310, 2021). "MET amplifications present a potential therapeutic target in non-small cell lung cancer." (PMID 34733418, 2021). "Furthermore, Champagnac and coworkers observed that genomic alterations affecting MET exon 14 are present in 2.6% of non-small cell lung cancer (NSCLC) patients." (PMID 33921709, 2021). "In non-small cell lung cancer, some of patients present MET mutation, including MET protein over expression, MET mutation or rearrangement, which lead to non-regulated downstream signaling pathway." (PMID 33928031, 2021). "In non-small cell lung cancer (NSCLC), KRAS is mutated in around one third of patients, much more frequently than other oncogenic drivers e.g. EGFR (~15%), ALK rearrangements (~5%), MET mutations (~3%), for which targeted therapies are available." (PMID 33466360, 2021). "Additionally, INC280 has shown promising clinical efficacy in non-small-cell lung carcinoma with MET amplification." (PMID 31776899, 2020). "Therefore, we assessed phosphorylation of endogenous IQGAP1 in non-small cell lung carcinoma (NSCLC) cell lines where MET signaling is up-regulated." (PMID 33087447, 2020).
non-small cell lung carcinoma (continued). "In fact, MET amplification has been also described in diverse tumor types, such as non-small cell lung cancer (NSCLC), gastric cancer, esophageal cancer, colorectal cancer, medulloblastoma, and glioblastoma, and has been associated with bad prognosis and poor survival." (PMID 32102486, 2020). "An in vivo model of adaptive resistance to MET TKIs was generated by long term administration of the maximum tolerated dose of a MET inhibitor in mice bearing a subcutaneous tumor xenograft of a non-small cell lung cancer (NSCLC) cell line, until resistance onset." (PMID 30927908, 2019). "Furthermore, we have performed FISH for MET on two primary non-small-cell lung cancer resection samples showing a MET high-level amplification in the metachronous metastasis." (PMID 30459450, 2019). "Finally MET (hepatocyte growth factor receptor) is considered a molecular target in several cancers, including non-small cell lung cancer, gastrointestinal cancer, and hepatocellular carcinoma." (PMID 30233579, 2018). "Multitargeted small molecule tyrosine kinase inhibitors of dual ALK and c-MET inhibition have been studied and FDA approved in non-small cell lung cancer and c-MET inhibition may be a potential therapeutic target in human lymphomas." (PMID 29854308, 2018). "Furthermore, miR-449a downregulation in non-small cell lung cancer correlated with the presence of lymph node metastasis, poor survival, and c-MET repression." (PMID 26934316, 2016). "With the aim to gain a better insight into the prognostic value of the copy number or protein expression of the MET gene for survival of patients with non-small cell lung cancer, we conducted the first comprehensive meta-analysis of published literature on this topic." (PMID 24922520, 2014). "In non-small cell lung cancer (NSCLC), both the over-expression of epidermal growth factor receptor (EGFR) and MET have been implicated in transformation, and it has been suggested that the inhibition of EGFR can be bypassed by activated MET." (PMID 21980431, 2011). "Furthermore, MET amplified non-small cell lung cancers have been shown sensitive to MEK inhibition." (PMID 38183207, 2025). "Activating somatic missense mutations with a carcinogenic effect have also been described in the N-domain of MET in sporadic papillary renal carcinomas and non-small-cell lung cancer, although, unlike activating missense variants in the tyrosine kinase domain, they were ligand-dependent." (PMID 40564049, 2025). "Non-small cell lung carcinoma (NSCLC) therapy has been transformed by the identification of actionable oncogenic driver mutations, of which ALK, ROS1, RET fusions and MET exon 14 skipping represent interesting drug targets." (PMID 38492039, 2024). "For example, the systemic treatment of advanced non-small cell lung cancer remained conventional chemotherapy for several decades until the emergence of TKI therapy following the discovery of several driver mutations including EGFR, ALK, ROS1, MET, RET, BRAF, and ERBB2/HER2." (PMID 39409947, 2024). "In addition to common EGFR activation mutations, targets such as ALK rearrangement, ROS1 rearrangement, RET rearrangement, BRAF V600E, MET exon 14 skip mutation, KRAS G12C, etc. have been gradually approved for targeted drug application in advanced non-small cell lung cancer." (PMID 38023198, 2023). "Tepotinib is an oral, highly selective MET inhibitor approved in Brazil, Canada, Great Britain, Japan, Switzerland, Taiwan, and the USA for the treatment of patients with unresectable, advanced or metastatic non-small cell lung cancer (NSCLC) and MET exon 14 (METex14) skipping alterations." (PMID 35771259, 2022). "Clinically relevant CNVs include ERBB2 amplification in breast cancer and EGFR and MET amplifications as a resistant mechanism in non-small cell lung carcinoma (NSCLC)." (PMID 35626061, 2022).
non-small cell lung carcinoma (continued). "Additionally, in a phase II study using the same anti-MET therapeutic antibody (in combination with erlotinib) in patient with advance non-small cell lung cancer, MET expression, as accessed by immunohistochemistry, represented a robust predictor of OS and PFS." (PMID 32659961, 2020). "Of note, the activation of MET by HGF has been suggested as a potential mechanism of acquired tyrosine kinase inhibitor (TKI) resistance to gefitinib in epidermal growth factor receptor (EGFR)-mutant non-small cell lung cancer (NSCLC) and to vemurafenib itself in BRAF-mutant melanoma." (PMID 33553157, 2020). "Moreover, a non-small cell lung cancer specimen was examined by using MET/CEP7 probes." (PMID 31101839, 2019). "The ALK/MET/ROS1 inhibitor crizotinib is approved for the treatment of non-small cell lung carcinoma (NSCLC) with ALK translocations and is also being tested in neuroblastoma (clinical trial: NCT00939770)." (PMID 29515255, 2018). "We sequenced KRAS and investigated expression of NQO1 and five clinically relevant proteins (DNMT1, DNMT3a, ERK1/2, c-MET, and survivin) in 108 patients with non-small cell lung carcinoma (NSCLC)." (PMID 25222473, 2014). "A similar approach is taken toward MET, HER2, RET, ROS1, and FGFR alterations as emerging targets in non-small-cell lung cancer." (PMID 39941723, 2025). "Amivantamab (EGFR/MET) combines receptor inhibition with ADCC and has shown efficacy in non-small-cell lung cancer with EGFR exon-20 insertions." (PMID 41262250, 2025). "Crizotinib is an oral small-molecule tyrosine kinase inhibitor of the ALK, MET, and ROS1 kinases, approved in ALK-positive non-small cell lung cancer." (PMID 38928438, 2024). "The interaction between MET and EGFR significantly contributes to the progression and drug resistance in non-small cell lung carcinoma (NSCLC)." (PMID 39769452, 2024). "Researchers have investigated the effectiveness of LY2801653, a potent inhibitor that targets both MET and RON tyrosine kinase receptors, which are known to be overexpressed in non-small cell lung cancer (NSCLC)." (PMID 39130630, 2024). "In a non-small cell lung cancer (NSCLC) study, the authors were able to detect different gene signatures related to therapy resistance (MET and HER3) and the initiation of metastasis (ALHD1) using CTCs." (PMID 38539545, 2024). "The MET RTK operates as an oncogenic driver in distinct types of cancers, such as non-small cell lung cancer and gastrointestinal carcinomas." (PMID 38957115, 2024). "In non-small cell lung cancer (NSCLC), SIPA1 expression is correlated with that of receptor tyrosine kinases, especially HGF/MET and TJs, which regulates barrier function and cell invasion and overexpression of SIPA1 leads to the promotion of NSCLC metastasis." (PMID 37500797, 2023). "In non-small cell lung cancers (NSCLC), MET overexpression has been found with a varying frequency of 35–72% through immunohistochemistry (IHC)." (PMID 37296895, 2023). "The two molecules, c-MET and HGF have an increased expression in various cancers such as non-small cell lung carcinoma (NSCLC), gastric, ovarian, pancreatic, thyroid, breast, head and neck, colon, and kidney carcinomas." (PMID 35626056, 2022). "In gefitinib-resistant non-small cell lung cancer cells, SNX1 was found to inhibit the endocytosis and degradation of MET whose overexpression was believed to be responsible for gefitinib resistance in non-small cell lung cancer." (PMID 35715463, 2022). "In Non-Small Cell Lung Cancer (NSCLC), MET amplification drives EGFR-inhibitor resistance by activating EGFR-independent phosphorylation of ErbB3 and downstream activation of the PI3K/AKT pathway." (PMID 36432631, 2022). "Targeted therapy for non-small-cell lung cancer (NSCLC) involves drugs that inhibit angiogenesis, and inhibitors of kinases EGFR, ROS1, MET, and RET." (PMID 35740471, 2022).
non-small cell lung carcinoma (continued). "Treatment planning for non-small cell lung cancer requires testing for EGFR, ALK, ROS1, BRAF, MET, RET and KRAS gene alterations." (PMID 34681592, 2021). "Crizotinib, commercialized as Xalkori®, is an oral receptor tyrosine kinase inhibitor (TKI) targeting MET, RON, and ALK that was approved by the FDA for the treatment of non-small cell lung cancer in 2011." (PMID 31979110, 2020). "There are at present multiple small molecule agents/drugs that have been developed to inhibit c-MET, including crizotinib (XALKORI®) that is FDA approved for the treatment of ALK or ROS1 mutant expressing non-small cell lung cancer." (PMID 32983965, 2020). "The National Comprehensive Cancer Network (NCCN) guidelines recommend “broad molecular profiling”, including BRAF, ERBB2 (HER2), MET, RET, NTRK, and ROS1, in addition to EGFR and ALK for metastatic non-small cell lung cancer (NSCLC)." (PMID 32375398, 2020). "In non-small cell lung cancer (NSCLC), MET exon 14 (METex14) alterations are considered to be the primary driving mechanism of tumorigenesis." (PMID 33195182, 2020). "MET gene amplification is identified in 2–5% of gastric cancers, 2–4% of esophageal adenocarcinoma (EAC), 1–8% of non-small cell lung cancer (NSCLC), and 2–10% of colorectal cancers." (PMID 30885149, 2019). "For example, in non-small cell lung cancer cell lines, HIF-2α promotes the MET proto-oncogene expression and induces resistance to Gefitinib and Erlotinib." (PMID 31640284, 2019). "Similarly, in murine models of human non-small cell lung cancer, treatment with vandetanib and cediranib initially led to tumor regression followed by resistance to therapy and progression that was associated with upregulation of both HGF and its receptor, c-MET." (PMID 29996818, 2018). "Of particular interest is the fact that MET gene amplification and overexpression leads to resistance to anti-EGFR therapies in non-small cell lung cancer and in brain tumors through receptor co-activation with EGFR." (PMID 30227653, 2018). "We tested several c-MET inhibitors, including Crizotinib (Xalkori), an FDA-approved compound, for late-stage non-small-cell lung cancers that express the abnormal anaplastic lymphoma kinase." (PMID 28807782, 2017). "Here we consider polypharmacological targeting of protein kinases ALK, MET, and EGFR (and its drug resistant mutant T790M) in non small cell lung cancer as an example." (PMID 29086093, 2017). "Collectively, we discovered that miR-329 exerted its tumor suppressive effects on non-small cell lung cancer in vitro and in vivo by directly targeting the 3′-UTR of MET mRNA." (PMID 26909600, 2016). "The first-in-class inhibitor of ALK, c-MET and ROS1, crizotinib (Xalkori), has shown remarkable clinical efficacy in treatment of ALK-positive non-small cell lung cancer." (PMID 27483357, 2016). "MET overexpression has been reported in many human cancers, such as hepatocellular carcinoma (HCC) and non-small cell lung cancer (NSCLC), and correlates with poor prognosis." (PMID 27013592, 2016). "Crizotinib has been approved for the treatment of metastatic ALK-positive non-small cell lung cancer, but it is also a potent MET inhibitor and is undergoing phase I studies in patients with c-Met positive tumors." (PMID 25784650, 2015). "Crizotinib, a potent and specific small molecule inhibitor of both ALK and c-MET tyrosine kinases, was approved by the Food and Drug Administration (FDA) for the treatment of non-small-cell lung cancer (NSCLC) patients with ALK gene rearrangement (ALK+)." (PMID 24422905, 2014). "It has been shown in non-small cell lung cancer (NSCLC) that a receptor tyrosine kinase (RTK), MET, is a potential miR-203- targeted gene, and an inverse correlation between miR-203 and MET expression exists." (PMID 25004126, 2014).
non-small cell lung carcinoma (continued). "The most advanced molecule crizotinib, which targets the receptor tyrosine kinases ALK and c-MET, has been approved by the US Food and Drug Administration for the treatment of patients with ELM4-ALK positive non-small-cell lung carcinoma." (PMID 23646137, 2013). "Crizotinib, a dual MET/ALK inhibitor, has demonstrated promising clinical activity in patients with non-small-cell lung cancer and inflammatory myofibroblastic tumors harboring ALK translocations." (PMID 22034911, 2011). "Indeed, the resistance of non-small cell lung cancer (NSCLC) to several RTK inhibitors, including those targeting EGFR-, ALK-, and MET-signaling, has been shown to result from EMT." (PMID 40943068, 2025). "An example of the success of this approach is illustrated by Amivantamab (Rybrevant), which targets epidermal growth factor (EGFR) and tyrosine kinase receptors (c-MET) (EGFR x c-MET) and was approved in May 2021 for non-small cell lung cancer treatment." (PMID 41250091, 2025). "Since LECT2 was reported to antagonize MET receptor activation in hepatocellular carcinoma and non-small cell lung cancer, we speculated that LECT2 might regulate FOXM1 signaling by targeting MET." (PMID 33937262, 2021). "Crizotinib, a TKI for which we have shown promising in vitro results for the treatment of GC presenting MET amplification/overactivation, is already in clinical setting for the treatment of EML4-ALK–translocated (ALK-positive) non-small cell lung cancer (NSCLC) patients." (PMID 31979110, 2020). "Although c-Met as a target in non-small cell lung cancer (NSCLC) showed promise based on preclinical data, clinical responses in NSCLC patients have been disappointing in the absence of MET mutation or MET gene amplification." (PMID 30134579, 2018). "Unfortunately, the c-MET inhibitor onartuzumab did not exhibit any clinical benefit when administered in combination with a bevacizumab regimen to advanced non-small cell lung cancer (NSCLC) patients." (PMID 29670046, 2018). "Around 80% of lung cancers are non-small-cell lung cancers (NSCLC), whose management remains challenging despite recent advances based on tumor genetic stratification using relevant biomarkers, such as EGFR, ALK, ROS-1, MET and KRAS2." (PMID 28860486, 2017). "in non-small cell lung cancer demonstrated that CAFs promote ANXA2 expression and phosphorylation via secretion of hepatocyte growth factor (HGF) and insulin-like growth factor 1 (IGF-1), activating c-MET and IGF-1R receptors, thereby enhancing the epithelial–mesenchymal transition (EMT) process." (PMID 40837013, 2025). "Likewise, it has been found that the newer targeted therapy, including inhibitors of EGFR, ALK, PI3K/AKT/mTOR, RAS-MAPK, RET, MET, BRAF, and NTRK/ROS1, as well as PD1 and CTLA4 molecules, for non-small cell lung cancer (NSCLC) have far better treatment responses than the standard therapies." (PMID 39157206, 2024). "Therefore, it is not surprising that MET gene amplification is also involved in the EGFR kinase inhibitor resistance in non-small-cell lung cancer (NSCLC) and colon cancer." (PMID 35158868, 2022). "Accordingly, crizotinib, an FDA-approved drug used for the treatment of patients with ALK-positive and ROS1-positive non-small cell lung carcinoma (NSCLC), triggered the nuclear translocation of FOXO3 suggesting an important role of RTKs such as ALK, MET or ROS1 in the regulation of FOXO3." (PMID 36080182, 2022). "To analyze whether MET high-level amplification may represent a late event in the carcinogenesis, we have performed FISH for MET on 25 independent cases of therapy-naive resection specimens of non-small-cell lung cancer in early stage: in none of them a high-level amplification is detectable." (PMID 30459450, 2019). "Three patients’ tumors (25, 26, and 29, with renal cell carcinoma, unspecified carcinoma, and non-small cell lung carcinoma, respectively) showed an EMT shift without having quantifiable levels of phospho-MET." (PMID 34180036, 2021).